ENSG00000259553 (novel transcript)
Gene: Long non-coding RNA gene on chromosome 15 (101,959,227 to 101,963,416, reverse strand). Ensembl gene ENSG00000259553.
Gene Ontology:
Biological process: miRNA-mediated post-transcriptional gene silencing